UCHL1 (ubiquitin C-terminal hydrolase L1)
Diseases named in the same sentence as UCHL1 in open-access papers (continued):
Sharing a sentence is not in itself a finding about the gene and the disease.
tumor (continued). "We found that UCHL1 is downregulated in PCa due to promoter hypermethylation and demonstrated that UCHL1 has tumour suppressor activity in LNCaP cells." (PMID 21999842, 2011). "We observed that UCHL1 expression directly correlated (P<0.001) with tumor grade, gender and Ki67 expression, while USP9X expression directly correlated with Ki67 expression (P<0.001)." (PMID 21283576, 2011). "Further validation of UCHL1 protein expression in a new independent set of samples confirmed that 32 out of 40 patients with lower UCHL1 levels in tumour tissue than in the surrounding benign prostate epithelium." (PMID 21999842, 2011). "Expression profiling data from various tumour types reported that UCHL1 is either up- or downregulated due to promoter hypo- or hypermethylation depending on the type of malignant tissue." (PMID 21999842, 2011). "We have recently demonstrated a heterogeneous expression pattern of UCHL1 mRNA and/or protein in both RCC cell lines and RCC lesions, which is associated with the RCC subtype, VHL status and with tumor progression." (PMID 19857250, 2009). "UCHL1 has been demonstrated to be either overexpressed or silenced in both tumor lesions and/or tumor cell lines of distinct origin." (PMID 19857250, 2009). "In some tumor entities a hypermethylation of UCHL1 was demonstrated in the primary tumor suggesting a tumor suppressor gene activity, whereas in other tumor types UCHL1 was highly overexpressed as a cause/consequence of the transformation process." (PMID 19857250, 2009). "Notably, even among patients with low UCHL1 expression, tumor stage and Lauren classification remained significantly associated with clinical prognosis." (PMID 41155583, 2025). "Hence, UCHL1 promotes tumor growth, suggesting it as a potential therapeutic target in cancer therapy." (PMID 41155583, 2025). "Its elevated expression may contribute to tumor progression and influence patient prognosis, suggesting a potential interaction with UCHL1." (PMID 41155583, 2025). "UCHL1 has predominantly been studied in the neurological and cardiovascular fields, especially for its role in tissue repair, and in oncology, with both pro- and anti-tumoral cancer-specific functions described." (PMID 38538704, 2024). "Hypoxic microenviroments in tumours and scar tissue along with high level expression of UCHL1 may therefore contribute to fibroblast diversity and functionality through targeted modulation of gene expression." (PMID 38808772, 2024). "Conversely, PAK4 and UCHL1 showed elevated levels in NATs compared to tumor samples." (PMID 39199615, 2024). "Consistently, UCHL1 overexpression drives NE markers in CRPC‐adeno tumor xenograft models in vivo." (PMID 39372390, 2024). "Our results suggest that UCHL1 may contribute to tumor progression in HCC by stabilizing PKM2 via deubiquitination, thereby providing important indications into the potential molecular mechanism of HCC pathogenesis." (PMID 38806474, 2024). "Therefore, we next aim to explore the association between UCHL1-mediated PKM2 deubiquitination and tumor prognosis as well as overall survival." (PMID 38806474, 2024). "CHGA and UCHL1 expression were related to tumour size and tumour stage LNM in CRC." (PMID 37246623, 2023). "Highly specialised neurons, diffuse neuroendocrine system cells, and their tumours express UCHL1." (PMID 36982508, 2023). "The high expression of UCHL1 in OS observed in this study suggests that it may play a role in tumor progression." (PMID 37575253, 2023). "Alternatively, a mechanism of the Wnt/β‐catenin signalling pathway may upregulate CHGA and UCHL1 at the transcriptional level and to influence the processes of tumour microenvironment formation and metastasis." (PMID 37246623, 2023).
tumor (continued). "Similarly, combinatory PKM2 siRNAs treatment also reversed the promotive influences on tumor migration and invasion provided by UCHL1 overexpression vector transfection alone." (PMID 37815895, 2023). "In contrast, UCHL1 overexpression significantly enhanced tumor cell expansion." (PMID 37815895, 2023). "Subsequent IHC assay also indicated consistent UCHL1 elevation in tumor tissues." (PMID 37815895, 2023). "The functional role of CHGA and UCHL1 in tumour growth, migration and invasion of CRC is still unknown." (PMID 37246623, 2023). "Additionally, patients with advanced pathologic stages, lymph-vascular invasion, and histologic stages exhibited significantly increased tumor UCHL1 expression level." (PMID 37815895, 2023). "Moreover, to examine the impact of UCHL1 modulation on tumor migration and invasion, wound healing assays in combination of Transwell/invasion assays were subsequently performed." (PMID 37815895, 2023). "UCHL1, a member of deubiquitinating enzymes, plays a key role in tumor growth and metastasis." (PMID 35655081, 2022). "The current research is focused on how to interfere with the regulation of UCHL1 in tumor cells." (PMID 35546675, 2022). "It has been found that UCHL1 is highly expressed in different kinds of tumor cells." (PMID 35546675, 2022). "Moreover, clinical studies displayed that the patients with higher expression of UCHL1 had lager tumor size and more advanced stage and more metastatic lymph nodes, which is consistent with the results of our study." (PMID 35655081, 2022). "In hepatocellular carcinoma, the UCHL1 gene is related to the apoptosis feature in tumor cells." (PMID 34769401, 2021). "It indicated that UCHL1 can be used as a potential predictor of tumor prognosis." (PMID 34016791, 2021). "Subsequently, there are conflicting reports that UCHL1 is a tumor suppressor or oncogene." (PMID 31906456, 2020). "In addition, the percentage of tumor cells positive for cyclin B1 was positively correlated with UCHL1 staining intensity in our validation cohort of USC samples." (PMID 31906456, 2020). "Furthermore, the volumes of the popliteal lymph nodes were bigger, and the pan-cytokeratin-positive tumor cells were more in the UCHL1 knockdown group than in the shControl group." (PMID 32120844, 2020). "Such discrepancy between studies may be explained by the discovery of various distinct downstream signaling pathways of UCHL1 in different tumor types, indicating that its net effect is highly context-specific." (PMID 31906456, 2020). "The development of additional UCHL1 inhibitors with increased specificity and vehicles to deliver the drug specifically to the tumor may increase the efficacy and lower the toxicity of the drug for clinical use." (PMID 31906456, 2020). "Several previous studies showed that UCHL1 is a tumor suppressor in several cancer cells." (PMID 31240215, 2019). "UCHL1 is also a tumor suppressor in a broad range of cancers including PCa." (PMID 31495056, 2019). "Intervening UCHL1 by shRNA as well as the small specific molecular inhibitor could significantly inhibit RA-induced neural differentiation in NB tumor cells, characterized by decreased neurite outgrowth and neural differentiation markers." (PMID 30359286, 2018). "As expected, inhibition of UCHL1 could significantly inhibit RA-induced neural differentiation of NB tumor cells, characterized by decreased neurite outgrowth and neural differentiation markers." (PMID 30359286, 2018). "As expected, inhibiting UCHL1 by knockdown or LDN57444 could significantly inhibit RA-induced neural differentiation of NB tumor cells, characterized by decreased neurite outgrowth and neural differentiation markers." (PMID 30359286, 2018). "As expected, inhibition of UCHL1 could significantly inhibit RA-induced neural differentiation of NB tumor cells." (PMID 30359286, 2018). "UCHL1 has multiple roles in ubiquitin homeostasis, protein stability and tumor progression." (PMID 29126443, 2017).
tumor (continued). "However, the influence of UCHL1 on HIF-1α expression observed in the present study appeared to be greater in clinical tumour tissues than in cancer cells cultured under simple low-oxygen conditions." (PMID 25615526, 2015). "Meanwhile, blockade of the UCHL1–HIF-1 axis suppresses the formation of metastatic tumours." (PMID 25615526, 2015). "Ubiquitin carboxyl- terminal esterase L1 (UCHL1) is a tumor suppressor silenced by promoter methylation in multiple cancers, but its role and alterations in breast tumorigenesis remain unclear." (PMID 22279545, 2012). "However, the epigenetic disruption of UCHL1 in breast tumorigenesis and its potential as tumor marker remain ambiguous." (PMID 22279545, 2012). "Although, previous data demonstrate a putative role of UCHL1 in different tumor types, the exact oncogenic mechanism remains unclear." (PMID 21999842, 2011). "The initial downregulation of UCHL1 by DNA promoter methylation might provide a growth advantage for these tumor cells and thus represent a tumor escape mechanism since the antigen cannot be recognized by the immune system." (PMID 19857250, 2009). "Since UCHL1 (over)expression frequently occurs during tumor progression this protein might be beneficial for the progression and metastases formation process in certain cancers." (PMID 19857250, 2009). "If UCHL1 methylation is RCC-related, detection of UCHL1 DNA promoter methylation in addition to the existence of UCHL1-specific autoantibodies detected in sera of tumor patients may further help to define patients with poor prognosis." (PMID 19857250, 2009). "UCHL1 expression was found in all 32 tumor adjacent kidney epithelium samples." (PMID 19857250, 2009). "Similarly, treatment with LDN-57444, a specific UCHL1 inhibitor, also suppressed tumor growth." (PMID 41155583, 2025). "Moreover, it has been reported that the decrease of UCHL1 may increase the sensitivity of the interaction between anti-tumor drugs and tumor cells." (PMID 35546675, 2022). "Since the expression DCX and UCHL-1 may increase the ability of BPDCN tumor cells to disseminate to distant organs, globally worsening patient outcome, both genes, as already suggested for NLGN4X and EDN3, may be regarded as possible therapeutic targets to arrest BPDCN dissemination." (PMID 34572907, 2021). "Moreover, UCHL1 can act as an mTOR inhibitor 45, and may protect tumor cells via activation of autophagy, which could offset PEM-induced apoptosis." (PMID 32483437, 2020). "In addition, restoration of UCHL1 inhibits tumor invasion and metastasis in vitro and in vivo." (PMID 33585209, 2020). "UCHL1 could be an oncogene or a tumor suppressor in dependent of tumor types." (PMID 32801299, 2020). "However, it remains to be seen whether UCHL1 is upregulated when tumor cells reach the omental site, or if tumor cells with higher expression in the primary tumor have a survival advantage when reaching the omental site." (PMID 31906456, 2020). "Therefore, this study confirms that UCHL1 occupies a tumor suppressor role in NPC metastasis by mediating CTTN degradation, and may represent a novel therapeutic target for NPC treatment." (PMID 32120844, 2020). "However, it has also been found that promoter hypermethylation mediated silencing or low expression of UCHL1 were also found in multiple tumors, including ovarian, nasopharyngeal, gastric, prostate, esophageal, hepatocellular and breast cancers, indicating UCHL1 as a tumor suppressor." (PMID 30359286, 2018). "Moreover, decreased UCHL1 expression correlated significantly with advanced tumor stages." (PMID 30359286, 2018). "Some of them are known to affect cellular growth/proliferation: SHISA3 is a known tumor suppressor, APBB2 plays a role in Alzheimer’s disease and the cell cycle, and UCHL1 promotes cellular proliferation in cancer." (PMID 40930101, 2025).
tumor (continued). "UCHL1 and ELAVL4, the “old” TAAs, are well-recognized biomarkers involved in deubiquitination and RNA translation processes, both of which contribute to tumor cell proliferation and survival." (PMID 39661479, 2025). "Top hits include changes in transcriptional regulation (ZNF385B, SNORA65), tumour microenvironment (COL1A2, COL3A1), and metastatic processes (UCHL1, SUCNR1, THY1)." (PMID 40890143, 2025). "Taken together, these proteomic results suggest that pharmacologic inhibition of UCHL1 leads to pronounced implications in cell metabolism in HGSOC, particularly in tumor cells that possess a chemoresistant phenotype." (PMID 40078282, 2025). "And we also analyzed the TCGA data and found that the mRNA expression levels of UCHL1 and PJA2 in tumor are lower than those in normal tissue, consistent with their protein expressions." (PMID 38918720, 2024). "UCHL1’s interaction with KDM4B is crucial for CCRCC malignancy and targeting UCHL1 has been shown to suppress tumor growth and enhance sensitivity to bevacizumab." (PMID 39199615, 2024). "UCHL1 knockdown slows the proliferation of TNBC cells and sensitizes the tumor cells to Tamoxifen and Fulvestrant." (PMID 38468288, 2024). "Conversely, ELN, EFEMP1, and UCHL1 were expressed at low levels, whereas TP63 was expressed at high levels in tumor tissues in contrast with ANT." (PMID 37441420, 2023). "In this study, we reported for the first time that UCHL1 upregulation is characteristic in UBC cancer cells and it plays an oncogenic role in the tumor progression and invasion." (PMID 37815895, 2023). "Within the group of patients with locoregional recurrence (n = 38), we observed not only a significant delay in tumor relapse for UCHL1-related HNSC, but also a shift from UCHL1-related to others phenotype in 66% of cases." (PMID 36980544, 2023). "Next, in order to explore the impact of UCHL1 expression on UBC patients’ disease stage and prognosis, in silico analysis on public TCGA platform UBC tumor mRNA-seq datasets were subsequently performed." (PMID 37815895, 2023). "The enzyme ubiquitin C-terminal hydrolase L1 (UCHL1), which is part of the deubiquitinase (DUB) family of enzymes, acts as an oncogenic promoter or a tumor suppressor depending on the specific type of cancer being considered." (PMID 37441420, 2023). "To detect UCHL1 expression in primary HNSC, we conducted an immunohistochemical staining on tumor sections." (PMID 36980544, 2023). "No neural cells were found in the microenvironment of BPDCN patient samples, but tumor cells showed expressions of DCX (11/15) and UCHL-1 (15/15), which are neural markers involved in neurogenesis." (PMID 35954431, 2022). "Collectively, these results highlighted the neural-oriented transcriptional program of a BPDCN tumor with the expression of well-known neural genes (EDN3, NLGGN4X, UCHL-1, and DCX) and the activation of neural receptor genes (Ach receptors)." (PMID 35954431, 2022). "Some DUBs, including UCHL1, BAP1 and CYLD, are described as displaying intrinsic oncogenic or tumor suppressor activities." (PMID 34315490, 2021). "Instead, the tumor cells themselves turned out to express neural markers; 11/15 cases stained for DCX (6/11 at high score level) and all cases were positive for UCHL-1 (6/15 cases at high level)." (PMID 34572907, 2021). "It was reported that UCHL1 is silenced by promoter CpG hypermethylation in a large panel of primary tumors including HNSCC cell lines and primary tumors, suggesting a tumor-suppressive function." (PMID 33585209, 2020). "Taken together, our findings suggest that UCHL1 contributes to USC tumorigenesis by stabilizing cyclin B, promoting cell cycle progression and tumor growth, and contributing to poor patient survival rates in USC patients." (PMID 31906456, 2020). "Since USP1 is known to act in an oncogenic manner while UCHL1 and UBL4A are shown to have tumor-suppressive functions, we focused our studies on how USP1 alters TAZ." (PMID 33114077, 2020).
tumor (continued). "A previous study has demonstrated that UCHL1 stabilized HIF-1α by abrogating the von Hippel-Lindau-mediated ubiquitination of HIF-1α, which subsequently promoted tumor metastasis." (PMID 32483437, 2020). "UCHL1, also known as PGP9.5, is prevalently methylated in various cancers, including CRC, and its tumor suppressor function has been experimentally demonstrated." (PMID 31064417, 2019). "OR-2003, but not OR-2100, displayed luciferase activity comparable to that of DAC and a stronger induction of endogenous tumor-suppressor genes, SFRP1 and UCHL1." (PMID 31370878, 2019). "We, therefore, hypothesize that BAP1 may have a similar function as UCHL1 and that loss of BAP1 alleviates the suppression pathways leading to activation of NF-κB, resulting in the production of cytokines and chemokines that attract tumor-specific T cells into UM." (PMID 28391358, 2017). "Co-expression of PRR11, UCHL1, EGR1, and SNAT1 was found to be a frequent event in HC tumor samples, indicating a cross-talk among these four proteins." (PMID 25971332, 2015). "Levels of ubiquitin-C-terminal hydrolase-L1 (UCH-L1), which catalyzes hydrolysis of C-terminal ubiquitin esters and amides, increase in various cancers, especially during tumor invasion and metastasis." (PMID 25915537, 2015). "Under these conditions, one of the most significant advancements of this study is the mechanistic and functional link detected between UCHL1 and HIF-1 in distant tumour metastasis." (PMID 25615526, 2015). "UCHL1 promoter methylation is an independent prognostic factor for ESCC survival and thus a valuable tumor marker for ESCC progression." (PMID 22279545, 2012). "In seven cases (UCHL1, USP9X, USP11, USP10, USP22, COPS5 and COPS6), dysregulation was observed in more than one tumor type." (PMID 21283576, 2011). "Mechanistically, UCHL1 interacted with CIP2A as a DUB, thereby promoting tumor progression in GC." (PMID 41155583, 2025). "In addition to the link between UCHL1 and HIF in promoting the expression of a subset of pro-fibrogenic genes, there is a clear link between UCHL1 and HIF activity in a variety of tumour types." (PMID 38808772, 2024). "Both TCGA and GTEx are derived from bulk tissue sequencing and represent the comprehensive expression of various cells, so they do not truly reflect the expression of UCHL1 in tumor cells very well." (PMID 38468288, 2024). "UCHL1, as the regulatory molecule for PKM2 proposed by TransDSI, may also be used as a potential drug target for resistant tumor treatment." (PMID 38806474, 2024). "Noteworthily, UCHL1 and CHGA have never been implicated in migration and invasion of CRC and tumour growth in nude mice xenograft models of cancer." (PMID 37246623, 2023). "Correlation of UCHL1 and CHGA expression with EMT‐related carcinogenesis signalling pathways, as a prognostic and predictive biomarker by immunohistochemical assay in CRC tumour tissues with lymph node metastasis (LNM) Stage III." (PMID 37246623, 2023). "While 5 genes were downregulated in tumor tissues, including PLAT, ERBB2, CEACAM1, NOX4, and UCHL1." (PMID 37056778, 2023). "Additionally, UCHL1-related HNSC, which had tumor recurrence after radiotherapy, showed a shift from UCHL1-related to the other phenotype, indicating the survival and clonal expansion of RT-resistant cancer cells lacking a UCHL1-related phenotype." (PMID 36980544, 2023). "Then PKM2 overexpression vectors/siRNAs were transfected into T24 and J82 cells with or without UCHL1 shRNAs to explore PKM2 regulation on UBC tumor cellular proliferation." (PMID 37815895, 2023). "NEC-like IDH2 and NEC-like SMARCA4/ARID1A tumors also demonstrated strong overexpression of proteins specific for neurons or cells of the diffuse neuroendocrine system such as UCHL1, CRMP1 and ENO2, strongly indicating a neuroendocrine differentiation for both tumor classes." (PMID 36443295, 2022).